INS (insulin)
Diseases named in the same sentence as INS in open-access papers (continued):
Sharing a sentence is not in itself a finding about the gene and the disease.
type 1 diabetes (continued). "Type 1 diabetes mellitus (T1D) is an endocrine disorder in which pancreatic β-cells stop producing insulin, typically due to autoimmune destruction." (PMID 36313762, 2022). "Although viruses have long been implicated in pancreatic beta cell destruction in type 1 diabetes, recent studies show that SARS-CoV-2 can infect, replicate, and destroy beta cells that produce insulin in pancreatic islets." (PMID 35360001, 2022). "This approach afforded some improvements in quality of life to people with type 1 diabetes as the amount of endogenously produced insulin required to metabolise very limited quantities of dietary carbohydrates, was also significantly reduced." (PMID 36676967, 2022). "The authors believe that C-peptide has a significant function in supporting insulin action with multiple beneficial effects on diabetic polyneuropathy and diabetic encephalopathy in type 1 diabetes." (PMID 36359305, 2022). "Since ever the pancreatic insulin was purified in 1922 by Leonard Thompson, the insulin-based formulations have been well established for type-1 diabetes." (PMID 35279150, 2022). "Type 1 diabetes (T1D) is an autoimmune disease resulting from the destruction of insulin-producing beta cells in pancreatic islets." (PMID 35874740, 2022). "In this systematic review and meta-analysis, we found that inhaled insulin is equally effective as subcutaneously administered insulin in patients with diabetes type 1." (PMID 35509734, 2022). "Type 1 diabetes is characterized by autoimmune destruction of pancreatic beta cells and perinatal cells can be harnessed both to generate insulin-producing cells for beta cell replenishment and to regulate autoimmune mechanisms via immunomodulation capacity." (PMID 36498923, 2022). "In contrast to hyperglycaemia, acute insulin-induced hypoglycaemia (blood glucose ~2.0–2.6 mmol/l) robustly accelerates gastric emptying in individuals with type 1 diabetes, even in those with cardiovascular autonomic neuropathy and gastroparesis." (PMID 36194250, 2022). "Type 1 diabetes is a challenging disease, characterized by dynamic changes in the insulin need during life periods, seasons of the year, but also by everyday situations." (PMID 36619534, 2022). "Seventy‐four children (aged 1–7 years, type 1 diabetes duration ≥6 months, insulin pump use ≥3 months) were randomized to use either a hybrid closed‐loop system (intervention) or sensor‐augmented pump therapy (control) for 16 weeks." (PMID 35561092, 2022). "Hypoglycemia-associated autonomic failure (HAAF) is a serious, life-threatening complication of intensive insulin therapy, particularly in people with type 1 diabetes." (PMID 36676967, 2022). "In the current study we attempted to emulate the features of human type 1 diabetes by supplementing the chow-fed STZ-diabetic rats with slow-release insulin implants." (PMID 36676967, 2022). "In patients with type 1 diabetes treated with multiple daily insulin injections or continuous subcutaneous insulin infusion, there is convincing evidence that the use of real‐time CGM can significantly reduce HbA1c and the risk of hypoglycaemia." (PMID 36251516, 2022). "Alterations in sleep habits are associated with high levels of Haemoglobin A1c (HbA1c) in young people with type 1 diabetes and with increased insulin requirements." (PMID 36291855, 2022). "In the last two decades, there has been an increasing number of patients using insulin pumps for the treatment of type 1 diabetes, owing to its ability to more closely simulate the physiologic pattern of insulin secretion." (PMID 35757419, 2022). "Type 1 Diabetes (T1D) is a chronic autoimmune disorder resulting from T cell-mediated destruction of the insulin-producing β cells found in the pancreatic islets." (PMID 36059452, 2022). "From a clinical point of view, absolute differences of around 4 mg·dL−1 play an insignificant role in yielding wrong therapeutic decisions, e.g., insulin injections in type 1 diabetes." (PMID 35590794, 2022).
type 1 diabetes (continued). "A growing number of Type-1 Diabetes (T1D) patients globally use insulin pump technologies to monitor and manage their glucose levels." (PMID 36107913, 2022). "Both groups were comparable in terms of sex distribution, median age, BMI, preoperative tumor marker, ASA score, and insulin/non-insulin-dependent diabetes." (PMID 34910230, 2022). "As expected, newly diagnosed patients with type 1 diabetes were preferentially treated with insulin." (PMID 35721726, 2022). "Over the past two decades, research has identified multiple immune cell types and soluble factors destroying insulin-producing β cells in type 1 diabetes." (PMID 35992113, 2022). "On the other hand, insulin conjugated to GLUT inhibitors has been employed for drug depots, half-life extension, and drug release, a strategy to mitigate the insulin-induced hypoglycemia in type 1 diabetic mouse model." (PMID 35552392, 2022). "It has been proposed that the insulin-producing cells in a malignant insulinoma and type 1 diabetes suggest that the insulin-producing malignant cells must have escaped autoimmune attack that otherwise had completely destroyed the beta cells of the patient." (PMID 34583764, 2021). "Standard insulin therapy to treat type 1 diabetes (T1D) consists of exogenous insulin administration through the subcutaneous (SC) tissue." (PMID 34564415, 2021). "Individuals with type 1 diabetes (5–10% of the diabetic population) are dependent on insulin intake for survival." (PMID 34959301, 2021). "Type-1 diabetes (T1D) or insulin-dependent diabetes is an autoimmune condition requiring external administration of insulin for the regulation of blood glucose." (PMID 34934084, 2021). "The use of automated insulin delivery systems has become a reality for people with type 1 diabetes (T1D), with several hybrid systems already on the market." (PMID 34770425, 2021). "Type 1 diabetes (T1DM) is a chronic autoimmune condition due to the destruction of insulin-producing beta cells in the pancreas." (PMID 34821673, 2021). "Type 1 diabetes (T1D) is an autoimmune disease characterized by T-cell-dependent immune destruction of insulin-producing beta-cells, leading to dysregulated glucose homeostasis." (PMID 34421931, 2021). "Both male and female offspring from type 1 diabetes dams showed reduced insulin secretion responded to oral glucose." (PMID 34177815, 2021). "Autoimmune, or type 1 diabetes, is characterized by selective destruction of insulin-producing pancreatic β-cells that is preceded by an inflammatory reaction in and around the islets of Langerhans." (PMID 33883217, 2021). "The result is that individuals with type 1 diabetes must carefully deliver insulin in relationship to their meals and exercise to manage their blood glucose." (PMID 33931977, 2021). "Another explanation is the high proportion of people discussing the injustice of the high cost of insulin for type 1 diabetes." (PMID 33496671, 2021). "Type 1 diabetes is defined as an immune system attack on the cells that make insulin in the pancreas." (PMID 34463627, 2021). "Type 1 diabetes mellitus (T1D) is an autoimmune disorder in which the host immune system mistakenly destroys the insulin‐secreting β cells located within the pancreatic islets of Langerhans." (PMID 33544449, 2021). "Self-care for youth with type 1 diabetes during this transition period includes the management of increased insulin demand due to drastic hormonal changes and the unstable glucose levels potentially caused by alcohol and substance use." (PMID 34281086, 2021). "It is known from the literature that the main ways of the destruction of beta cells, decreased synthesis, and secretion of insulin in type 1 diabetes is largely determined by the influence of ROS and TNF-α." (PMID 34572994, 2021). "Prandial insulin is administered around mealtime and is a component of therapy for most patients with type 1 diabetes." (PMID 34174848, 2021).
type 1 diabetes (continued). "Mentions of herbal treatments centered around a news story about the death of a person with type 1 diabetes whose herbalist advised the person to stop his/her insulin." (PMID 33496671, 2021). "Insulin was administered to every patient with type 1 diabetes, with 52–68% treated with a basal–bolus regimen and 17–24% treated with a premix insulin regimen." (PMID 33594476, 2021). "In nearly all patients diagnosed with type 1 diabetes before the age of five, the presence insulin-specific antibodies has been reported, which suggests a significant role of peptides originating from insulin in the pathogenesis of the disease." (PMID 34836227, 2021). "The benefits of carbohydrate restriction in type 1 diabetics reduces the error in determining insulin amount to match the increased blood glucose since dramatic spikes are less likely." (PMID 34068325, 2021). "Conventional insulin therapy (CT) with two daily injections of premixed insulin is used in individuals with type 1 diabetes only in exceptional circumstances." (PMID 34301317, 2021). "There are several treatment methods to control the sugar levels and insulin concentrations for patients with the type 1 diabetes." (PMID 33800659, 2021). "In contrast, those with low C-peptide levels were less obese, had relatively normal lipid levels, and required more frequent use of insulin; thus, this group appeared to share more type 1 diabetes characteristics." (PMID 34879878, 2021). "Currently, the standard treatment for type 1 diabetes is the lifelong administration of exogenous insulin." (PMID 34594393, 2021). "All patients were classified by the local clinical teams as having type 1 diabetes and were confirmed to be receiving insulin therapy." (PMID 33966090, 2021). "Our findings provide some insight into type 1 diabetes by suggesting that the exposure to exogenous insulin seems to be a more important factor in the development of obesity than the ghrelin system." (PMID 34294136, 2021). "We compared polyclonal Tregs, which are a cellular medicinal product used in the treatment of type 1 diabetes, with Tregs specific and unspecific against whole insulin (index INS) or insulin β chain peptide 9-23 (index B:9-23)." (PMID 33868279, 2021). "Stem cell therapy using islet-like insulin-producing cells derived from human pluripotent stem cells has the potential to allow patients with type 1 diabetes to withdraw from insulin therapy." (PMID 34202521, 2021). "Stem cell derived insulin producing cells or islets have shown promise in reversing Type 1 Diabetes (T1D), yet successful transplantation currently necessitates long‐term modulation with immunosuppressant drugs." (PMID 34155834, 2021). "Previous studies have reported positive effects of PA on insulin requirements, the lipid profile, physical fitness, muscle strength, and the risk of developing cardiovascular disease in people with type 1 diabetes mellitus (T1DM)." (PMID 33860058, 2021). "T2D (also called non-insulin-dependent diabetes) occurs due to inadequacy of the body to effectively utilize insulin." (PMID 34616293, 2021). "Apart from obvious medical reasons should individuals with type 1 diabetes be actively involved in decision making to find the optimal insulin strategy." (PMID 34301317, 2021). "Type 1 Diabetes (T1D) is a potentially life-threatening multifactorial autoimmune disorder characterized by T-cell-mediated destruction of pancreatic β cells, resulting in a deficiency of insulin synthesis and secretion." (PMID 33794915, 2021). "An additional factor is our revised approach to treatment of type 1 diabetes, specifically with insulin therapy." (PMID 33828529, 2021). "Insulin-dependent diabetes mellitus (also known as type 1 diabetes) is sensitive to insulin therapy." (PMID 34201520, 2021). "Over the past decades, several new technologies have been developed to improve management of type 1 diabetes, including insulin pumps and real-time continuous glucose monitoring (CGM) devices." (PMID 33996702, 2021).
type 1 diabetes (continued). "In summary, no clear advantage exists in favour of one or the other way to apply insulin in type 1 diabetes." (PMID 34301317, 2021). "Type 1 diabetes results from an autoimmune destruction of insulin-producing beta cells in the pancreatic islets of Langerhans, and is characterised by circulating islet autoantibodies to beta cell antigens." (PMID 33515070, 2021). "The successful treatment of type 1 diabetes (T1D) requires those affected to employ insulin therapy to maintain their blood glucose levels as close to normal to avoid complications in the long-term." (PMID 33462097, 2021). "Both innate and adaptive immune cells are critical players in autoimmune destruction of insulin-producing β cells in type 1 diabetes." (PMID 33690220, 2021). "Type 1 diabetes (T1D), previously termed as juvenile diabetes, represents a complex, multi-factorial, autoimmune disorder, characterized by an impaired production and release of insulin by the beta cells of the islets of Langerhans in the pancreas." (PMID 34557162, 2021). "In type 1 diabetes (T1D), transplantation of insulin-secreting β-cells to restore the insulin level is commonly used." (PMID 34281227, 2021). "The IF-DIABETE system is an insulin bolus dose support, considered as the first bolus calculator dedicated to people with type 1 diabetes, designed in the Arabic language, and adapted to the large Arabic food culture." (PMID 33585132, 2021). "Research suggests that as many as 60% of people with type 1 diabetes (T1D) admit to misusing insulin." (PMID 34121470, 2021). "Hybrid closed-loop insulin delivery systems are gradually transforming clinical management of type 1 diabetes." (PMID 33550442, 2021). "Type 1 diabetes (T1D) is an autoimmune disease in which insulin-producing β cells are destroyed, leading to lifelong insulin deficiency." (PMID 33671312, 2021). "Type 1 diabetes mellitus (T1DM) is characterized by the autoimmune destruction of insulin-producing beta-cells within pancreatic islets." (PMID 34350161, 2021). "Type 1 diabetes (T1d) results from a sustained autoreactive T and B cell response towards insulin-producing β cells in the islets of Langerhans." (PMID 34745148, 2021). "While higher affinity GADA predicts progression to type 1 diabetes, and in both adult cohorts reported here, an increased requirement for insulin treatment, measurement of GADA affinity is time consuming and expensive with limited clinical applicability." (PMID 34272582, 2021). "Along one end of the spectrum is type 1 diabetes (T1D) where insulin producing beta (β)-cells are destroyed by cellular autoimmune mechanisms." (PMID 33981301, 2021). "Regular exercise is beneficial and recommended for people with type 1 diabetes, but increased glucose demand and changes in insulin sensitivity require treatment adjustments to prevent exercise-induced hypoglycemia." (PMID 34489869, 2021). "For patients with type 1 diabetes, the administration of insulin, dietary controls and regular physical activity can achieve “near normoglycaemia”." (PMID 34684518, 2021). "Phase 3 trials of insulin icodec compared to degludec are being studied in adults with type 1 diabetes (NCT04848480)." (PMID 37745178, 2021). "The aim of this study was to compare individuals with type 1 diabetes with continuous subcutaneous insulin infusion (CSII) and intensified insulin therapy (ICT) in routine care regarding metabolic control and treatment satisfaction." (PMID 34301317, 2021). "For autoimmune diseases, tolerance is reflected in reduced need for disease-modifying therapy or prolonged improvement of disease manifestations, such as retention of residual insulin secretion in type 1 diabetes." (PMID 34616405, 2021). "The MiniMed 670G hybrid closed-loop system by Medtronic was the first second-generation, closed-loop APDS approved by the FDA to automatically monitor glucose and administer appropriate basal insulin doses in people 14 years or older with type I diabetes." (PMID 33679974, 2021).